FCGBP (Fc gamma binding protein)
Diseases named in the same sentence as FCGBP in open-access papers (continued):
Sharing a sentence is not in itself a finding about the gene and the disease.
spinal cord ependymoma (1 paper, 2025). An ependymoma that arises from the spinal cord. "Recurrent HRNR and FCGBP mutations observed in spinal cord ependymomas have also been reported in other tumor types." (PMID 41160379, 2025).
systemic sclerosis (1 paper, 2021). A chronic disorder, possibly autoimmune, marked by excessive production of collagen which results in hardening and thickening of body tissues. "Circulating FCGBP associated with systemic sclerosis was speculated to arise from intestinal goblet cells." (PMID 34332619, 2021).
tumor (40 papers, 2010 to 2026). "IgG Fc binding protein (FCGBP), known as a tumor suppressor in various cancers, has also been implicated in drug resistance." (PMID 41560312, 2026). "Most markers were strongly associated with the FCGBP level in HNSC, suggesting that FCGBP was strongly associated with tumor-infiltrating immune cells in HNSC." (PMID 35626334, 2022). "We found that FCGBP expressions were strongly and distinctly linked to the expressions of known immunological checkpoints, and FCGBP expression had significant positive connections with tumor mutational burden." (PMID 35733916, 2022). "FCGBP expression is correlated with higher immune infiltration and better prognosis in various cancer types and its down regulation is associated with an immunosuppressive tumor microenvironment." (PMID 40264151, 2025). "The FCGBP gene encodes a high molecular weight glycoprotein that binds to the Fc portion of immunoglobulin-G and plays an important role in innate mucosal epithelial defense, but also influences tumor metastasis and tumor immunity." (PMID 40264151, 2025). "Given the pivotal role of chronic inflammation in tumor development, dysregulated FCGBP may be implicated in the carcinogenesis of CRC." (PMID 38709264, 2024). "Possibly, this is why FCGBP is associated with the tumor microenvironment." (PMID 38396056, 2024). "Besides, high FCGBP expressions were associated with immunosuppressive tumor microenvironment characteristics." (PMID 35733916, 2022). "The difference in FCGBP expression levels in different tumor types may reflect distinct underlying functions and mechanisms." (PMID 33686968, 2021). "FCGBP is initially detected in the intestinal epithelium, playing a vital role in innate mucosal epithelial defense, metastasis, and tumor immunity." (PMID 40084401, 2025). "The outcomes of this work exhibited a substantial link between FCGBP and M2 macrophages in the tumor microenvironment." (PMID 38396056, 2024). "Extensive research has extensively documented the varied levels of FCGBP expression across diverse tumor types." (PMID 38709264, 2024). "Subsequent investigations have unveiled that FCGBP expression significantly correlates with tumor metastasis and reduced overall survival in patients with CRC." (PMID 38709264, 2024). "The levels of tumor‐infiltrating CD4 + cells, CD8 + T cells, dendritic cells, macrophages, NK cells, and plasma cells were substantially linked to FCGBP expression (all p < 0.05)." (PMID 38396056, 2024). "The FCGBP expression and prognostic significance in tumor tissue were investigated in this research work." (PMID 38396056, 2024). "These collective findings suggest a potential significant role for FCGBP in the EMT process during tumor progression." (PMID 38709264, 2024). "In the multivariate analysis, both high FCGBP immunoexpression and a low tumor regression grade independently emerged as unfavorable prognostic factors for all three endpoints (all p ≤ 0.025)." (PMID 38709264, 2024). "(Purpose) Previous studies have pointed out the significance of IgG Fc binding protein (FCGBP) in carcinogenesis, cancer progression, and tumor immunity in certain malignancies." (PMID 35626334, 2022). "This review summarizes the functional relevance and role of FCGBP in immune responses and disease development, and highlights the potential role in diagnosis and predicting tumor prognosis." (PMID 35936008, 2022). "LinkedOmics performed Gene enrichment analysis, and TISIDB and TIMER2.0 evaluated the role of FCGBP in the tumor microenvironment." (PMID 35626334, 2022). "After adjusting for tumor purity, 51 of 57 immune cell markers shows significant positive correlation with FCGBP, suggesting that FCGBP plays an important role in immune cell infiltration into the microenvironment of CRC." (PMID 35936008, 2022). "Cell adhesion in the vasculature of specific organs is a critical step in tumor metastasis, and FCGBP expression significantly increases cell adhesion." (PMID 35936008, 2022).
tumor (continued). "FCGBP's role in the immunological mechanism and immune response of the tumor microenvironment (TME) was examined via studying the correlations between FCGBP expressions and TMB." (PMID 35733916, 2022). "The expression of the Fc fragment of IgG-binding protein (FCGBP) is low in some tumours and high in others." (PMID 35109839, 2022). "Of course, the broad relevance of FCGBP in tumor research is also discussed, to provide new insights into the various functions of this molecule." (PMID 35936008, 2022). "We identified 3 driver genes (FCGBP, GRIN2B, and FRY), and recurrent truncating mutations in FRY impaired its tumor-suppressive function and promoted tumor proliferation." (PMID 35993362, 2022). "Exploring the roles of FCGBP is critical due to the tumor microenvironments’ impact on carcinogenesis and tumor progression." (PMID 35626334, 2022). "Oncomine online database was utilized to analyze the mRNA expression level of FCGBP in tumor and normal tissues." (PMID 35047393, 2021). "This indicates that high expression of FCGBP promotes the polarization of macrophages, which is closely related to the immunosuppressive state of the tumor." (PMID 33686968, 2021). "The Tumor Immune Estimation Resource (TIMER) tool was used to determine the correlations of FCGBP expression with tumor immune infiltration." (PMID 35047393, 2021). "TIMER data analysis revealed that FCGBP was significantly lower expressed in most tumor tissues compared with normal tissues." (PMID 35047393, 2021). "Through the GEPIA database, we evaluated the transcription level of FCGBP in different tumor tissues and normal tissues." (PMID 35047393, 2021). "The expression levels between the primary tumor and the liver metastases were overall similar; only FCGBP was downregulated in the liver metastases." (PMID 27340863, 2016). "In this model, low expression of FCGBP (IgGFc‐binding protein) and VSIG2 (V‐set and Ig domain‐containing protein 2) was associated with tumor progression, but their roles and mechanisms in GC remain unclear." (PMID 40084401, 2025). "At the univariate level, elevated FCGBP immunoexpression, low tumor regression grade, advanced post-CRT tumoral status, positive post-CRT lymph node status, and the presence of vascular invasion were significantly and adversely associated with all three endpoints (all p ≤ 0.0434)." (PMID 38709264, 2024). "Notably, FCGBP expression was negatively correlated with enriched tumor-infiltrating macrophages and paclitaxel resistance." (PMID 38396056, 2024). "Moreover, strong evidence of low FCGBP expression in HNSC tumor tissues was found from our HNSC patient cohorts by immunohistochemistry." (PMID 38396056, 2024). "The data demonstrated that tumor progression and poor prognosis in HNSC patients with low FCGBP expression might partially be linked to macrophages enriched in the tumor immune microenvironment." (PMID 38396056, 2024). "Elevated FCGBP immunointensity correlated with lymph node involvement before treatment (p = 0.001), tumor invasion, and lymph node involvement after treatment (both p < 0.001), vascular invasion (p = 0.001), perineural invasion (p = 0.041), and reduced tumor regression (p < 0.001)." (PMID 38709264, 2024). "FCGBP has been proven to participate in intestinal tumor immunity." (PMID 38750571, 2024). "Two genes, TFF3 and FCGBP, were downregulated in Xenopus tumor and upregulated in human cancer." (PMID 37580380, 2023). "The ROC analysis revealed that the different FCGBP expression levels could effectively distinguish the tumor tissues from the normal tissues (area under the curve [AUC]: 0.647)." (PMID 36803544, 2023). "FCGBP may be involved in the tumor microenvironment of HNSC to regulate cancer development because cytokines and chemokines are critical noncellular components of the tumor microenvironment." (PMID 35626334, 2022). "FCGBP is also involved in regulating the infiltration of immune cells into tumor microenvironments." (PMID 35936008, 2022).
tumor (continued). "Thus, we analyzed the composition of tumor-infiltrating immune cells correlating to FCGBP levels in HNSC samples." (PMID 35626334, 2022). "Although the existence of FCGBP has been reported for more than 20 years, and a key role being suggested in regulating the tumor immune microenvironment, the physiologic functions of FCGBP are still not fully elucidated in intestinal mucosal defense and in cancer biology." (PMID 35936008, 2022). "In CRC, FCGBP abundance shows inverse correlation with tumor purity and macrophage expression but coincides with a high number of B cells, suggesting that FCGBP may be involved in humoral immune responses in this cancer." (PMID 35936008, 2022). "Moreover, the correlation between FCGBP and immunosuppressive gene expression indicates that FCGBP plays a key role in regulating tumor immunology." (PMID 33686968, 2021). "Excess dietary iron in tumor tissues was also associated with significant changes (generally, increases; p ≤ 0.05) in proteins involved in modulating cell protein integrity (HSPA5, HSPA9, ITGB1, PSMA4, DPP7, and PEPD), cell mobility and growth (CAPZB), and immunologic factors (FCGBP)." (PMID 38732562, 2024). "Additionally, FCGBP expression could effectively distinguish tumor tissues from normal tissues, which was verified by qRT-PCR." (PMID 36803544, 2023). "CIBERSORT algorithm was used to analyze the fraction of tumor-infiltrating immune subsets, and 21 different types of immune cell profiles in OSCC patients were completed to further validate the association between FCGBP expressions and the immune microenvironment." (PMID 35733916, 2022). "The functional analysis revealed that FCGBP may related to tumor immune response." (PMID 35047393, 2021). "Together, FCGBP could be a tumor suppressor and novel biomarker for CRC." (PMID 31956350, 2020). "Mechanistically, FCGBP modulated the PIGR/JAK2/STAT3 signaling pathway, thereby exerting both anti-tumor and anti-CDDP resistance effects." (PMID 41560312, 2026). "The AUC value of the model consisting of the four genes (CHI3L1, FCGBP, VSIG2, and TFF2) outperformed other tumor markers and performed well in predicting the prognosis of GC patients." (PMID 40084401, 2025). "While the precise function of FCGBP in response to radiotherapy and/or chemotherapy remains incompletely understood, as these treatments induce DNA damage in cancer cells, FCGBP may contribute to tumor resistance against these DNA toxins by forming a molecular shield." (PMID 38709264, 2024). "An increased expression of FCGBP, BPIFB, F5, CST1, and CFB and their correlation to epithelial-to-mesenchymal transition (EMT) under clinorotation were detectable as potential tumor suppressor biomarkers." (PMID 37048115, 2023). "Additionally, FCGBP may regulate the tumor microenvironment." (PMID 35626334, 2022). "In addition, FCGBP may participate in the immune response in the tumor microenvironment of HNSC." (PMID 35626334, 2022). "Conversely, the clear majority of the 10 most abundant human-derived gene products detected exclusively in tumor parenchyma (e.g., CEACAM5, MUC5B, FCGBP) were found to be involved in metastasis." (PMID 29899869, 2018). "In general, the low level of FCGBP expression may lead to a certain level of paclitaxel resistance in HNSC cells and enhance their immunosuppressive capacity against anti-tumor cells." (PMID 38396056, 2024). "Although panomics revealed low RNA and protein expression of CA1, CLCA1, MATN2, AHCYL2, and FCGBP in malignant tissues compared to healthy colon mucosa, no differentially expressed RNA or protein targets were detected between tumour and metastatic tissues." (PMID 36691026, 2023). "Alterations in FCGBP, FLG, KCNJ12, and KCNJ18 were observed in all tumor samples." (PMID 37182141, 2023). "Interestingly, we observed increased expression of FCGBP, BPIFB, F5, CST1, and CFB and their correlation to EMT under SMG, rendering them potential tumor suppressor biomarkers." (PMID 36613598, 2022).
tumor (continued). "We also report for the first time that two CRC driver gene, FCGBP and NBPF1 might function as tumor suppressors and prognostic markers for CRC." (PMID 31956350, 2020). "First, alterations in FCGBP, FLG, KCNJ12, and KCNJ18 were observed in all tumor samples, regardless of the responsiveness towards HIPEC." (PMID 37182141, 2023). "The expression levels of FCGBP, PABPC1 and NDRG1 were higher and the expression levels of ADH1A, CYP3A4 and ADH1B were lower in tumour tissues than in adjacent nontumour tissues." (PMID 35109839, 2022).
cancer (26 papers, 2007 to 2026). A tumor composed of atypical neoplastic, often pleomorphic cells that invade other tissues. "Further investigation into the correlation between FCGBP expression levels and the therapeutic efficacy of chemotherapy and radiotherapy holds the potential to yield novel insights into cancer treatment." (PMID 38709264, 2024). "The researchers also performed GO and KEGG analysis and found that FCGBP play a role in cancer‐related biological processes, such as apoptosis and biosynthetic processes." (PMID 39428571, 2024). "Similar to other mucins, FCGBP acts as a crucial mediator between an inflammatory milieu and a sustained physiological response, a process essential for cancer development and progression." (PMID 38709264, 2024). "The three-gene methylation model features FCGBP (IgG Fc binding protein), which has been demonstrated to enhance cancer infiltration and metastasis." (PMID 39484038, 2024). "The first step in exploring the potential features of FCGBP in pan-cancer was to analyze its expression in 22 prevalent types of malignancy." (PMID 38396056, 2024). "In pan-cancer tissues, the expression of FCGBP and the survival status of patients were analyzed using information from The Cancer Genome Atlas (TCGA) and Gene Expression Omnibus (GEO)." (PMID 38396056, 2024). "The Fc fragment of IgG binding protein (FCGBP) has been confirmed to play an important role in various cancers." (PMID 36803544, 2023). "Clarifying these questions will help us understand the relevance of FCGBP in inflammatory disorders and cancer." (PMID 35936008, 2022). "The potential roles of FCGBP in cancer initiation, progression, and prognoses have been proposed in certain malignancies." (PMID 35626334, 2022). "FCGBP, or the Fc fragment of IgG binding protein, is a mucin-like glycoprotein found in body fluid and thought to play important roles in immunity and cancer." (PMID 36613598, 2022). "We further analyzed the relationship between FCGBP and immunosuppressive genes using TCGA pan-cancer data." (PMID 33686968, 2021). "The interaction between FCGBP expression and the genes regulating metabolism in cancer cells may contribute to CRT resistance." (PMID 38709264, 2024). "The results revealed different FCGBP expression in various cancer types." (PMID 36803544, 2023). "For example, FCGBP was an independent prognostic factor for both HPV-related and HPV-unrelated HNSCs since the HPV status may cause a distinct difference in cancer behaviors of HNSC." (PMID 35626334, 2022). "(Results) The expression level of FCGBP is lower in cancer tissues." (PMID 35626334, 2022). "Furthermore, cancer progression and the formation of metastatic lesions leads to further significant reduction, highlighting the role of FCGBP in oncogenesis and cancer progression." (PMID 35936008, 2022). "Subsequent investigations have demonstrated the potential importance of FCGBP in several cancers." (PMID 35626334, 2022). "Similar to the conditions of the gallbladder- and colorectal- cancers, FCGBP may participate in regulating HNSC metastasis through epithelial-mesenchymal transition (EMT)." (PMID 35626334, 2022). "Since protein–protein interaction is essential in the molecular mechanisms underlying carcinogenesis and cancer progression and aggressiveness, aberrant FCGBP expression may regulate cancer behaviors by functional interactome linking with TFF3." (PMID 35626334, 2022). "We first assessed FCGBP expression in pan-cancer data from TCGA and GTEx." (PMID 33686968, 2021). "Therefore, it is urgent to clarify the role of FCGBP in cancer prognosis, progression, and treatment." (PMID 33686968, 2021). "In cancer, FCGBP has been widely found to be differentially low-expressed." (PMID 35047393, 2021). "Additional experiments are required to determine whether changes in the novel candidate cancer genes (FCGBP and TLE2) are indeed oncogenic." (PMID 18688287, 2007). "Additionally, pan-cancer FCGBP expression was examined using Cox survival analysis." (PMID 38396056, 2024).
cancer (continued). "The FCGBP, F13A1, FRY, and TMLHE genes had significantly higher expression in normal tissues than in cancer (P = 2.8e-07, P = 3.3e-14, P < 2.22e-16 and P < 2.22e-16, respectively)." (PMID 40264151, 2025). "Among the seven subclusters of cancer cells, cancer cell subcluster 1 specifically expressed high levels of REG4, FCGBP and MUC2, which are considered markers of goblet cells." (PMID 36690709, 2023). "Although the roles of other genes involved in the prognostic model have been relatively less explored, some bioinformatics analyses have identified the prognostic role of some of these genes, such as RTN4R, FCGBP, and FST, in OSCC or other types of cancers." (PMID 36185403, 2022). "FCGBP, FLNC, TLR7, and CSF2RA were potential antigens for developing cancer vaccination, and the patients in IS3 were considered the most suitable for vaccination in LGG." (PMID 34404444, 2021). "In addition to the role of FCGBP and BPIFB, the complement factor B (CFB) and the chimeric tumor suppressor 1 (CST1) are shown to exert protective roles in cancer." (PMID 36613598, 2022). "In HNSC, immunohistochemistry demonstrated that the FCGBP protein levels were lower in cancer tissues than noncancerous tissues retrieved from the surgical margin." (PMID 35626334, 2022). "Moreover, FCGBP correlates to TFF3, a prognostic biomarker in various cancers, at transcriptional and translational levels." (PMID 35626334, 2022). "Additionally, FCGBP might interact with TFF3, an essential protein in the pathogenesis of several cancers." (PMID 35626334, 2022).
infection (2 papers, 2021 to 2026). The state of being infected such as from the introduction of a foreign agent such as serum, vaccine, antigenic substance or organism. "An in vitro infection model was established using FCGBP-knockdown goat bronchial epithelial cells infected with P." (PMID 41847354, 2026). "Knockdown of FCGBP in goat bronchial epithelial cells leads to impaired cellular barrier function, resulting in excessive activation of type I interferon, HIF-1, TNF, and NOD-like receptor signaling pathways following infection with P." (PMID 41847354, 2026).
head and neck tumors (1 paper, 2024). "By analyzing data from patients with head and neck tumors, we discovered that FCGBP expression was linked to paclitaxel resistance." (PMID 38396056, 2024).